AQP4 (aquaporin 4)
Diseases named in the same sentence as AQP4 in open-access papers (continued):
Sharing a sentence is not in itself a finding about the gene and the disease.
glioma (continued). "Recent work supports the notion that intracellular volume regulation by NKCC1, as well as aquaporin 4 (AQP4), may indeed promote glioma cell invasion." (PMID 22570591, 2012). "Accordingly, in C6 cells and RG2 cells, two glioma cell lines of the rat, and in SMA mouse glioma cell lines, we found no AQP4 expression." (PMID 22590566, 2012). "However, exploring the precise mechanisms regarding the interaction between AQP4 and MMP-9 could be of great significance for revealing the roles of AQP4 redistribution in glioma progression and treatment." (PMID 39247976, 2024). "In the present work, we showed that the AQP4 aggregation into the pathogenic AQP4-tetramer and AQP4-OAPs differently affected the expression profile of KCNMA1, KCNJ11, ABCC8, and ABCC9 genes but not of the KCNJ8 gene in the U87 glioma cell, evaluated by the RTPCR gene expression." (PMID 39200356, 2024). "However, our study does not yet have enough data to decipher the effects of AQP4 on the growth and development of glioma cells or TAMs, and more extensive work is warranted for further investigation." (PMID 36599974, 2023). "However, few previous studies have put AQP4 and the glioma immune microenvironment together, and neither have they utilized single-cell sequencing analysis to reveal the AQP4 expression profile in malignant gliomas." (PMID 36599974, 2023). "Recognition of AQP4-specific inhibitors may pave the way for the creation of novel molecular targeting agents useful in the treatment of CNS cancers." (PMID 34113257, 2021). "The motility of glioma U87MG cells was increased when AQP4 was overexpressed or Kyn was supplemented, while Kyn supplementation could not restore the cell motility decreased by AhR inhibition and AQP4 knockdown." (PMID 32296044, 2020). "Interestingly, several of these L2b-targets, which are not bound by AGO2 in glioblastoma, are implicated in glioma, such as PCDH9 and AQP4 and show similar non-canonical target sites as we found in other L2-miRNA targets." (PMID 30865625, 2019). "In GSC glioma tissue, AQP4 was expressed on tumor cells, not tumor endothelial cells, and its expression levels decreased along with ADC levels, thus may not have contributed to edema." (PMID 31803626, 2019). "However, AQP4 expression is down-regulated in glioma patients without gender-dependent difference in AQP4 expression, although sex hormones such as estrogen, progesterone and testosterone modulate AQP4 expression in astrocytes." (PMID 31178701, 2019). "However, the AQP4 expression levels in glioma have not been fully elucidated; furthermore, the correlation of AQP4 expression with glioma malignancy remains controversial." (PMID 28423683, 2017). "The aim of the present study was to find out whether glioma cell lines which contain no AQP4 are capable of expressing this water channel after implantation into brain or flank." (PMID 22590566, 2012). "In this context, it is important to emphasize that despite of AQP4 expression including the M1- and M23-isoforms in animal glioma, no OAP formation could be observed in freeze fracture analysis." (PMID 22590566, 2012). "These cell cultures never stop expressing AQP4 in contrast to cultured glioma cells." (PMID 22590566, 2012). "Accordingly, in the present study we could show that AQP4 negative glioma cell cultures are capable of re-expressing AQP4 in vivo after orthotopic implantation." (PMID 22590566, 2012). "Furthermore, AQP4 protein expression in tumour tissue of gliomas of various degrees was not statistically unusual, and the grade of peritumoral oedema positively linked with AQP4 protein expression, which in turn connected with VEGF and hypoxia inducible factor 1 alpha (HIF-1) expression." (PMID 38336645, 2024).
glioma (continued). "And by modulating the polarity of AQP4, MMP-9 inhibition could facilitate the glymphatic clearance of cytokines, as well as the draining of macromolecules and traffic immunological cells from the CNS into cervical lymph nodes, being a candidate curing strategy against glioma." (PMID 39247976, 2024). "Thus, it could be assumed that in glioma cells, AQP4 might also exert activities independent of OAPs." (PMID 28423683, 2017). "Interestingly, the authors also indicated for the first time that AQP4-negative glioma cells implanted in the animal brain or flank could specifically express AQP4 in intracerebral gliomas but neither extracranial nor flank gliomas had detectable AQP4 expression." (PMID 28423683, 2017).
Cerebral ischemia (95 papers, 2007 to 2026). Restriction of arterial blood supply to the brain associated with insufficient oxygenation to support the metabolic requirements of the tissue. "Studies showed that the infarction manifested the diffuse elevation of AQP4 expression in the early stage after cerebral ischemia, which is a main cause of cellular edema." (PMID 40837880, 2025). "We demonstrated that melatonin effectively reduced post-injury activations of AQP4 and associated cytotoxic edema following permanent focal cerebral ischemia." (PMID 39457496, 2024). "In cerebral ischemia, lactic acidosis in astrocytes causes edema by increasing water permeability via aquaporin 4, the principal water channel in the brain, and excess glutamate release, thus leading to excitotoxicity." (PMID 38604775, 2024). "More recent research showed that loss of Cav-1 results in decreased AQP4 expression and impaired perivascular AQP4 covering after cerebral ischemia associated with altered reactive astrocyte morphology and enhanced brain swelling." (PMID 35873558, 2022). "Our method depicted the AQP4-expression-related temporal and spatial differences in water dynamics associated with focal cerebral ischemia." (PMID 36685250, 2022). "The lack of caveolin-1, in Cav-1−/− knockout mice resulted in decreased AQP4 expression and impaired perivascular AQP4 coverage after cerebral ischemia, which in turn is associated with increased brain swelling in this mouse type." (PMID 35454119, 2022). "Cerebral edema caused by AQP4 overexpression is the main determinant of progressive neuronal damage during cerebral ischemia." (PMID 35097126, 2022). "Here, neuroprotective and antiedematous action of erythropoietin has been linked with the preservation of AQP4 function in trauma, hydrocephalus, and cerebral ischemia." (PMID 34966347, 2021). "AQP4 gene knockout significantly reduced the cytotoxic CE caused by water intoxication, cerebral ischemia and brain trauma." (PMID 33235702, 2020). "Absence of Cav-1 was associated with perivascular changes in AQP4 expression and enhanced brain swelling at 3 days after cerebral ischemia." (PMID 32523952, 2020). "In summary, we show for the first time that loss of Cav-1 results in decreased AQP4 expression and impaired perivascular AQP4 covering after cerebral ischemia associated with altered reactive astrocyte morphology and enhanced brain swelling." (PMID 32523952, 2020). "Manley and colleagues established two models of cytotoxic edema, acute water intoxication and early cerebral ischemia, and demonstrated brain edema was significantly reduced in AQP4-deficient mice." (PMID 27529222, 2016). "Our study demonstrated that this process was highly associated with the upregulation of aquaporin-4 after cerebral ischemia." (PMID 27690011, 2016). "An example is that of miR-320a which targets multiple genes other than AQP4, in other pathways (inflammation, calcium signaling, cell cycle and apoptosis) associated with cerebral ischemia." (PMID 24961318, 2013). "AQP4 is a member of the transmembrane aquaporin family and the water/glycerol transporter family, and AQP4 gene deficiency ameliorates brain edema caused by cerebral ischemia." (PMID 34867166, 2021). "Besides, AQP-4 was also proven to be associated with cell apoptosis induced by cerebral ischemia –reperfusion injury." (PMID 29592873, 2018). "In addition, aquaporin-4-deficient mice are protected from cytotoxic edema produced by water intoxication and brain ischemia." (PMID 27690011, 2016). "However, under-expression of AQP4 protein is associated with early stage edema in rodents subjected to permanent focal brain ischemia and hypoxia-ischemia." (PMID 21119879, 2010). "Following cerebral ischemia, astrocytes alter the M23/M1 expression ratio, a transcriptional change that might mechanistically underlie observations that, in grey matter, CNS injury triggers a redistribution of Aqp4 away from the endfoot." (PMID 26419740, 2015).
Cerebral ischemia (continued). "The spatial and temporal characteristics of AQP4 polarization following cerebral ischemia, and its relationship with the ALPS index." (PMID 40837880, 2025). "This study aimed to evaluate the dynamic changes of the perivascular space diffusion index (index for diffusivity along the perivascular space, ALPS) and its relationship with aquaporin 4 (AQP4) polarization after cerebral ischemia in rats." (PMID 40837880, 2025). "Taken together, these results suggest that iNSCs can repair BBB injury after cerebral ischemia/reperfusion, possibly through intervention targeting AQP-4." (PMID 40530334, 2025). "Bumetanide has been demonstrated to prevent edema formation following brain ischemia by reducing AQP4 expression." (PMID 39944892, 2025). "AQP4 is overexpressed during the establishment of cerebral edema in acute damage events, such as brain trauma and cerebral ischemia." (PMID 39043897, 2024). "AQP4 overexpression is observed during the first 24 h after experimental cerebral ischemia and, an event related to the increase in water brain content." (PMID 39043897, 2024). "The immunofluorescence analysis revealed that AQP4 expression surrounding blood vessels was up-regulated following cerebral ischemia." (PMID 38438409, 2024). "Inhibition of the NLRP3 inflammasome plays a role in reducing brain edema after cerebral ischemia-reperfusion and also affects the distribution of AQP4." (PMID 39295943, 2024). "We herein present a study of the effect of TRPV4 and AQP4 channel deletion on astrocyte swelling and their ability to regulate cell volume under conditions modeling cerebral ischemia." (PMID 38818517, 2024). "In these AQP4−/− mice, the severity of acute brain injury after permanent focal cerebral ischemia is lessened due to reduced cytotoxic edema." (PMID 39457496, 2024). "Differently, inhibiting AQP4 has been observed to ameliorate cytotoxic edema encountered during cerebral ischemia." (PMID 39508543, 2024). "The involvement of AQP4 in acute brain injury has been validated using transgenic AQP4 knockout mice in a brain ischemia model." (PMID 39043897, 2024). "The neuroprotective activity of several molecules with antioxidant and anti-inflammatory properties in animal models of brain ischemia and TBI are associated with a reduction in AQP4 expression and activity." (PMID 39043897, 2024). "To assess the impact of brain ischemia on the expression of AQP4 and GDNF in EV cargo, we analyzed these proteins’ band intensities in the TEVs and ADEVs of AIS patients (D1, D7: n = 18, M1: n = 12) and compared them to those of the control subjects (n = 9)." (PMID 39596535, 2024). "One of the early responses after cerebral ischemia is astrocyte swelling, which is in part due to the translocation of AQP4 to the cell surface." (PMID 36258136, 2023). "In cerebral ischemia, AQP4 expression is upregulated, blood–brain barrier permeability is increased, and cerebral edema is induced." (PMID 35685645, 2022). "In VCI, the fascinating, complex role of AQP4 in cerebral ischemia and cerebral hemorrhage is also well known." (PMID 35111362, 2022). "The downregulation of miR-130b in astrocytes leads to the upregulation of water channel protein AQP4 and exacerbates brain injury in cerebral ischemia." (PMID 36710937, 2022). "Accumulating evidence had indicated that the amount of AQP4 expression was altered after cerebral ischemia." (PMID 37786741, 2022). "An animal study in a model of global cerebral ischemia suggests that there was strong neuroprotection and better survival outcome in AQP4 knock-out mice compared with the AQP4 + / + mice after arterial occlusion." (PMID 35755778, 2022). "Our study showed that the AQP4 protein level increased after tMCAO, and immunofluorescence staining indicated that the distribution of AQP4 around the blood vessels in mice after cerebral ischemia expanded and was distributed in the extravascular area." (PMID 35685645, 2022).
Cerebral ischemia (continued). "The aquaporin-4 observations in the knock-out mice with water intoxication and focal cerebral ischemia suggested that during vasogenic edema, water entered the brain tissues regardless of aquaporin-4, but left the brain with aquaporin-4." (PMID 35627746, 2022). "MALAT1 affects AQP4 expression by competitively binding to miR-145, thereby promoting cerebral ischemia-reperfusion injury." (PMID 36275741, 2022). "AZA reversibly inhibits water conduction using aquaporin-4 (AQP4), which has been implicated in cytotoxic brain edema resulting from water intoxication, brain ischemia, or meningitis." (PMID 35890028, 2022). "Most of the studies found that AQP4 inhibition, including AQP4 knockout or AQP4 gene silence using small interfering RNA (siRNA), reduced brain edema in different cerebral ischemia models." (PMID 34305569, 2021). "After cerebral ischemia, the expressions of AQP-4 and GFAP are upregulated, and the foot processes of astrocytes swell." (PMID 34975411, 2021). "The present study identified MALAT1 as a regulator of cerebral ischemia/reperfusion injury by regulating miR-145 to target AQP4." (PMID 32138732, 2020). "Here, we investigated if Cav-1 is involved in AQP4 expression and cellular distribution after brain ischemia relating to astrogliosis and brain swelling." (PMID 32523952, 2020). "miR-320a was reported to inhibit AQP1 and AQP4 gene expression both in vitro and in vivo in a cerebral ischemia rat model, whereas anti-miR-320a upregulated AQP1 and AQP4 expression with consequent reduction of infarct volume." (PMID 29977890, 2018). "A study using a rat model of cerebral ischemia/reperfusion showed that the neuroprotective effect of Rg1 against blood-brain-barrier disruption involves downregulation of brain AQP4 expression." (PMID 29721498, 2018). "Here, we aimed to assess the independent and combined effects of ginsenoside Rb1 (GRb1) and Emodin on neuroprotection through regulating Connexin 43 (Cx43) and Aquaporin 4 (AQP4) expression in cerebral ischemia/reperfusion (I/R) model rats." (PMID 30233364, 2018). "AQP4 plays an important role in the development of “cytotoxic” models of brain edema in cerebral ischemia, hyponatremia, and meningitis." (PMID 30483388, 2018). "AQP4 also play a role in pathophysiologic conditions, e.g. reduced edema formation after cerebral ischemia." (PMID 28399892, 2017). "The increase in Aqp4 expression level is observed in the brain parenchyma region in normally aged mice, whereas acute insults such as cerebral ischemia elevate Aqp4 expression level in the astrocytic-endfeet on glial limitans." (PMID 28148272, 2017). "Studies on AQP4 expression after cerebral ischemia have mainly been performed in animal or cell models." (PMID 29057271, 2017). "The effects of AQP4 on brain edema after cerebral ischemia are mainly investigated by AQP4 inhibition models, including AQP4 knockout, AQP4 depolarized distribution and AQP4 gene silencing." (PMID 27529222, 2016). "Meanwhile, brain water content was increased in wild type mice compared with AQP4 deletion mice at 3 days and 5 days after severe global cerebral ischemia produced by transient four-vessel occlusion." (PMID 27529222, 2016). "Melatonin is a tryptophan metabolite secreted by the pineal gland that has been observed to confer neuroprotective effects through the inhibition of AQP4 in models of early cerebral ischemia." (PMID 27438832, 2016). "As the most abundant AQP in the CNS, the expression of AQP4 is increased in three kinds of cerebrovascular diseases, including cerebral ischemia, ICH and SAH." (PMID 27529222, 2016). "This review focuses on expression of AQP4 and the effects of AQP4 on brain edema and neural cells injuries in cerebrovascular diseases including cerebral ischemia, intracerebral hemorrhage and subarachnoid hemorrhage." (PMID 27529222, 2016).